CACNA1B (calcium voltage-gated channel subunit alpha1 B)
Description:
Voltage-sensitive calcium channels (VSCC) mediate the entry of calcium ions into excitable cells and are also involved in a variety of calcium-dependent processes, including muscle contraction, hormone or neurotransmitter release, gene expression, cell motility, cell division and cell death. This alpha-1B subunit gives rise to N-type calcium currents. N-type calcium channels belong to the 'high-voltage activated' (HVA) group. They are involved in pain signaling. Calcium channels containing alpha-1B subunit may play a role in directed migration of immature neurons. Mediates Ca(2+) release probability at hippocampal neuronal soma and synaptic terminals (By similarity). [Isoform Alpha-1B-1]: Voltage-sensitive calcium channels (VSCC) mediate the entry of calcium ions into excitable cells and are also involved in a variety of calcium-dependent processes, including muscle contraction, hormone or neurotransmitter release, gene expression, cell motility, cell division and cell death. This alpha-1B subunit gives rise to N-type calcium currents.
Synonyms: BIII; CACNL1A5; Cav2.2; CACNN; DYT23; NEDNEH
Tractability: Small molecule: an approved drug acts on it; a structure with a bound ligand is known; a high-quality ligand is known; it belongs to a druggable protein family. Antibody: its Gene Ontology location is reachable by antibodies, with high confidence; UniProt predicts a signal peptide or a membrane-spanning region. PROTAC: ubiquitination databases record sites on it; its protein half-life has been measured; a small molecule that binds it is known. Other modalities: an approved drug acts on it.
Target class: Voltage-gated calcium channel; Ion channel; Voltage-gated ion channel
Gene: Protein-coding gene on chromosome 9 (137,877,782 to 138,124,624, forward strand). Ensembl gene ENSG00000148408.
Subcellular location: Membrane
Subcellular location (Human Protein Atlas): Acrosome; Cytosol; Equatorial segment
Pathways (Reactome):
Neuronal System: Presynaptic depolarization and calcium channel opening
Gene Ontology:
Molecular function: high voltage-gated calcium channel activity; protein binding; voltage-gated calcium channel activity; amyloid-beta binding; calcium ion binding; monoatomic ion channel activity
Biological process: modulation of chemical synaptic transmission; response to amyloid-beta; calcium ion import across plasma membrane; chemical synaptic transmission; positive regulation of calcium ion-dependent exocytosis of neurotransmitter; calcium ion transmembrane transport; monoatomic ion transport; transmembrane transport
Cellular component: membrane; neuronal cell body; plasma membrane; voltage-gated calcium channel complex; synapse
Genetic constraint (gnomAD): Loss-of-function variants: 53 observed, 156.89 expected, observed/expected ratio (o/e) 0.34, 90% interval 0.27 to 0.43. The upper end of that interval is the gene's LOEUF score, 0.43, which puts it in group 1 of 6, group 1 being the genes least tolerant of losing a copy. Missense variants: 1,978 observed, 2,415 expected, observed/expected ratio (o/e) 0.82, 90% interval 0.79 to 0.85. Synonymous variants: 1,029 observed, 950.6 expected, observed/expected ratio (o/e) 1.08, 90% interval 1.03 to 1.14.
Gene-disease validity (ClinGen):
ClinGen rates the evidence that CACNA1B causes each of these diseases.
complex neurodevelopmental disorder with motor features (autosomal recessive): Moderate. A complex neurodevelopmental disorder that involves more than one phenotype associated with the central nervous system, including but not limited to intellectual disability, autism, and seizures (epilepsy).
Homologues: Orthologues: macaque CACNA1B (99% identical), chimpanzee CACNA1B (96% identical), dog CACNA1B (94% identical), pig CACNA1B (94% identical), rat Cacna1b (92% identical), mouse Cacna1b (92% identical), guinea pig CACNA1B (89% identical), rabbit CACNA1B (85% identical), tropical clawed frog CACNA1B (70% identical), zebrafish cacna1ba (66% identical), zebrafish cacna1bb (66% identical). Paralogues in human: CACNA1A (64% identical), CACNA1E (56% identical), CACNA1D (35% identical), CACNA1C (35% identical), CACNA1F (34% identical), CACNA1S (33% identical), CACNA1H (23% identical), CACNA1I (23% identical), CACNA1G (22% identical), SCN2A (21% identical), SCN3A (21% identical), SCN1A (21% identical), and 14 more.
Diseases named in the same sentence as CACNA1B in open-access papers:
CACNA1B is named in the same sentence as 114 diseases in open-access papers, as found by Europe PMC text mining. Sharing a sentence is not in itself a finding about the gene and the disease. The quoted sentences say what the papers report.
epilepsy (10 papers, 2013 to 2025). A brain disorder characterized by episodes of abnormally increased neuronal discharge resulting in transient episodes of sensory or motor neurological dysfunction, or psychic dysfunction. "KDM5C gene silencing leads to down-regulation of SCN2A, CACNA1B; CACNA1H; SCL4A3, SLC18A1, and SLC6A12, All of these KDM5C target genes have been linked to neurological disorders such as epilepsy, autism or schizophrenia." (PMID 39948613, 2025). "Looking into the DEG subnetwork, we found that some well-known ASD candidate genes, such as Kcnma1, Shank2, Cacna1a and Cacna1b, and epilepsy candidate genes, such as Scn3a, Grin2a, Gabrg2, and Grin2b, are hub genes in this subnetwork." (PMID 32033586, 2020). "This review delves into the significance of the CACNA genes, including CACNA1A, CACNA1B, CACNA1C, CACNA1D, CACNA1E, CACNA1G, and CACNA1H, in the pathogenesis of conditions such as migraine, epilepsy, cerebellar ataxia, dystonia, and cerebellar atrophy." (PMID 38785745, 2024).
breast carcinoma (9 papers, 2015 to 2025). "Identification of the underlying role of CACNA1B in cancer development may also help in the discovery of new therapeutic targets for the treatment of prostate and breast cancer." (PMID 26147197, 2015). "Very little is known about its role in carcinogenesis, except overexpression of CACNA1B (Cav2.2) was detected in both prostate and breast cancer." (PMID 28127114, 2017). "Recent studies have identified CACNA1B (Cav2.2) being overexpressed in prostate and breast cancer tissues when compared to adjacent normal tissues; however, its role in non-small cell lung cancer (NSCLC) has not been investigated." (PMID 28127114, 2017). "Our results indicate that CACNA1F is highly expressed only in testis cancer and that CACNA1B is up-regulated only in breast cancer." (PMID 26147197, 2015). "Our data suggest that CACNA1B has high expression specifically in clinical prostate and breast cancer tissues." (PMID 26147197, 2015). "This bioinformatics analysis revealed that different subtypes of VGCCs (CACNA1C, CACNA1D, CACNA1B, CACNA1G, and CACNA1I) are implicated in the development and progression of diverse types of cancer and show dramatic up-regulation in breast cancer." (PMID 26147197, 2015). "CACNA1B, CDCA8, and RGMA were identified as prognostic factors and a promising therapeutical target in breast cancer." (PMID 40665355, 2025). "For instance, breast cancer showed dramatic upregulation of CACNA1C, CACNA1D, CACNA1B, CACNA1G, and CACNA1I." (PMID 26147197, 2015).
neuroblastoma (8 papers, 2011 to 2020). Neuroblastoma (NB) is the most common solid, extracranial childhood tumor. "We used the rat DRG/mouse neuroblastoma hybrid F11 cell line which expresses Cacna1b, to determine if CTCF binds Cacna1b e37a locus in a cell, and to test if CTCF levels influence Cacna1b e37a splicing." (PMID 32213287, 2020). "CACNA1B overexpression is associated with an unfavorable prognosis in non-small cellular lung cancer and altered expression of KIAA0513, due to an aberrant methylation pattern, correlated with non-survivors in Neuroblastoma." (PMID 31249626, 2019).
Dystonia (7 papers, 2019 to 2025). An abnormally increased muscular tone that causes fixed abnormal postures. "The causative role of CACNA1B (OMIM#601012) in the onset of myoclonus–dystonia was first proposed in a single family carrying the variant p.(Arg1389His)." (PMID 40724495, 2025). "Mutations in CACNA1B have been reported for, among others, dystonia 23, characterized by involuntary muscle contraction (omim.org/entry/614860)." (PMID 31254144, 2019). "Similarly, GRIN2A and CACNA1B mutations have been found in dystonia and other movement disorders." (PMID 35773312, 2022). "Both its mutation and the ANO3 mutation are associated with myoclonus‐dystonia.Although both ITPR3 and CACNA1B act on cytoplasmic calcium ion concentration, the specific effects of these mutations have not been confirmed in vivo, warranting further study." (PMID 37649308, 2023).
schizophrenia (6 papers, 2011 to 2026). A major psychotic disorder characterized by abnormalities in the perception or expression of reality. "In support of this, the CACNA1B gene, which codes for Cav2.2 channels, has been shown to be associated with schizophrenia." (PMID 39479264, 2024). "Moreover, Cacna1b has been associated with schizophrenia in three recent linkage studies." (PMID 22066001, 2011). "Thus, we may hypothesize that alterations in Cacna1e and Cacna1b affect hippocampal network activity such as to impair memory performance in, for example, schizophrenia patients known to suffer from memory impairment." (PMID 22066001, 2011).
Myoclonus-Dystonia (5 papers, 2015 to 2025). "Individuals affected by CACNA1B variants presented with epileptic encephalopathy, severe neurodevelopmental delay, hyperkinetic movement disorder (myoclonus-dystonia syndrome), postnatal microcephaly, and hypotony." (PMID 37095367, 2023). "Previous study has linked CACNA1B (Cav2.2) to neuropathic pain and CACNA1B (Cav2.2) mutation (R1389H) has been linked to myoclonus-dystonia syndrome, a rare movement disorder." (PMID 28127114, 2017). "Remarkably, SGCE, CACNA1B, and GRIN2A are well-known for causing Myoclonus-Dystonia (M-D), a hyperkinetic movement disorder that resembles tics, which is found in a subgroup of PANS." (PMID 35773312, 2022).
peripheral nerve injury (4 papers, 2013 to 2021). Injury to a peripheral nerve. "We showed that the increase in 5-mC at CpG sites in Cacna1b e37a locus following peripheral nerve injury, that induces long-lasting hyperalgesia, is associated with reduced Cacna1b e37a expression in Trpv1-lineage neurons." (PMID 32213287, 2020). "Injury-induced increased methylation levels of Cacna1b e37a locus likely underlies some of the chronic pathophysiology associated with peripheral nerve injury." (PMID 32213287, 2020). "dCAS9-TET1 has been used to correct disease-induced alterations in gene expression and mis-splicing events, raising the possibility that this approach could be used as a strategy to correct cell-specific alternative splicing of Cacna1b e37a in vivo following peripheral nerve injury." (PMID 32213287, 2020).
acute myeloid leukemia (3 papers, 2023). Acute myeloid leukemia (AML) is a group of neoplasms arising from precursor cells committed to the myeloid cell-line differentiation. "CACNA1B encodes a voltage-gated calcium channel subunit and GWAS Catalog records a strong association (scoring 12.2) between CACNA1B and acute myeloid leukemia, for which BMI is a known risk factor." (PMID 37205363, 2023).
bipolar disorder (3 papers, 2020 to 2025). A disorder of the brain that causes unusual shifts in mood, energy, activity levels and the ability to carry out day-to-day tasks. "Likewise, CACNA1B gene has also been linked to major depressive disorder and suicide and even to bipolar disorder." (PMID 39479264, 2024).
migraine (3 papers, 2021 to 2025). "For example, mutations in CACNA1B have been identified in families affected by migraine, while a polymorphism in CACNA1E (rs35737760) has been associated with patients exhibiting complex neurological aura phenotypes." (PMID 39997646, 2025). "Beyond CACNA1A, other genes within the CACNA family, such as CACNA1B (encoding CaV2.2) and CACNA1E (encoding CaV2.3), have also been implicated in the pathogenesis of migraine aura." (PMID 39997646, 2025). "Furthermore, different genetic variants of CACNA1B have been associated with migraine susceptibility, further highlighting the role of CACNA genes in migraine pathology." (PMID 38785745, 2024).
cardiac arrhythmia (2 papers, 2015 to 2023). Any disturbances of the normal rhythmic beating of the heart or MYOCARDIAL CONTRACTION. "For instance, a CACNA1B missense variant (c.4166G > A; p.Arg1389His) was reported in a family with adult-onset myoclonus-dystonia and cardiac arrhythmia, which resulted in lower current Cav2.2 channels, emphasizing the functional relevance of this paralog." (PMID 37845370, 2023).
channelopathies (2 papers, 2015 to 2023). "Given the clinical presentation pointing towards a possible channelopathy, the authors assumed that the causative variant was the one in CACNA1B." (PMID 26157024, 2015).
deafness (2 papers, 2014 to 2021). An inherited or acquired condition characterized by the complete loss of the ability to hear from one or both ears. "RIMBP2 is a member of a family of proteins that act as binding partners of the presynaptic active zone proteins RIMs as well as for voltage-gated Ca2+-channels, such as CACNA1B and CACNA1D, the latter already known to be involved in deafness." (PMID 24454846, 2014).
familial hemiplegic migraine (2 papers, 2016 to 2020). A migraine disorder characterized by individual and family history of aura that includes motor weakness. "CACNA1B is a member of a family of genes, which includes CACNA1A, that has been linked to a monogenic subtype of MTA, namely familial hemiplegic migraine (FHM)." (PMID 32968778, 2020).
Parkinson disease (2 papers, 2023 to 2024). A progressive degenerative disorder of the central nervous system characterized by loss of dopamine producing neurons in the substantia nigra and the presence of Lewy bodies in the substantia nigra and locus coeruleus. "The CREB5/CACNA1B/GNB4/PPP2R5A gene was found to be closely related to Parkinson’s disease in pathways of dopaminergic synapses." (PMID 37323142, 2023).
acute lymphoblastic leukemia (1 paper, 2023). Leukemia with an acute onset, characterized by the presence of lymphoblasts in the bone marrow and the peripheral blood. "The CACNA1B gene has been associated with acute lymphoblastic leukemia and myeloid leukemia through the regulation of immune functions and leukocyte chemotaxis." (PMID 36979105, 2023).
Adult onset (1 paper, 2021). Onset of disease manifestations in adulthood, defined here as at the age of 16 years or later. "Considering its putative role in some primary dystonia syndromes, we screened the CACNA1B gene for disease-causing variants using targeted NGS Ion Torrent PGM in a large cohort of patients with adult-onset IFD." (PMID 33051750, 2021).
anaplastic astrocytoma (1 paper, 2021). "Brain cancers, including glioblastoma, oligodendroglia, anaplastic astrocytoma, diffuse astrocytoma, and glioblastoma, show a significant reduction of cacna1b expression compared to the control groups." (PMID 33419226, 2021).
cardiac conduction disease (1 paper, 2013). "Finally, CACNB2 is associated with the regulator of the voltage-gated calcium channels RIM1, and with the sodium channel SCN2B, through its interaction with CACNA1B, since it has been described that a mutation in CACNB2b, and a mutation in SCN5A underlie cardiac conduction disease.." (PMID 24339868, 2013).
cerebral infarction (1 paper, 2016). An ischemic condition of the brain, producing a persistent focal neurological deficit in the area of distribution of the cerebral arteries. "Indeed, blockade of N-type VGCCs decrease neuronal damage associated with ischemic brain injury in animal models and the CACNA1B gene is associated with cerebral infarction in a human population." (PMID 27487831, 2016).
Crohn disease (1 paper, 2012). A gastrointestinal disorder characterized by chronic inflammation involving all layers of the intestinal wall, noncaseating granulomas affecting the intestinal wall and regional lymph nodes, and transmural fibrosis. "Interestingly, both LDLRAD3 and CACNA1B genes are involved in gastrointestinal diseases and polymorphisms in both these genes have been found to be associated with Crohn's disease making them both strong biological and positional candidates." (PMID 22396781, 2012).
diabetes (1 paper, 2023). "The CACNA1B gene located in 9q34.3 is involved in the N-type voltage-dependent calcium channel, which can cause beta cell dysfunction and death, and lead to both types 1 and 2 diabetes." (PMID 36979105, 2023).
gastric tumor (1 paper, 2021). "CACNA1B had accumulated somatic mutations in gastric tumor with H. pylori infection." (PMID 34521966, 2021).
hypertriglyceridemia (1 paper, 2024). A laboratory test result indicating elevated triglyceride concentration in the blood. "Specifically, compared to the control group, the expression of Cacna1c and Cacna1b, which was reported to be downregulated in hypertriglyceridemia subjects with decreased insulin secretion, was decreased in HFD mice." (PMID 38557554, 2024).
lung carcinoma (1 paper, 2017). "Future in vitro mechanistic studies are needed to determine whether CACNA1B (Cav2.2) regulates cell proliferation, apoptosis, or chemoresistance in lung cancer cells and whether CACNA1B (Cav2.2) influences the intracellular or ER Ca2+ levels." (PMID 28127114, 2017).
lymph node metastasis (1 paper, 2017). "Next, we correlated CACNA1B (Cav2.2) protein expression with NSCLC patients' clinical characteristics, including gender, age at diagnosis, tumor size, histopathology grading, lymph node metastasis, smoking history, and TNM stage." (PMID 28127114, 2017).
Obesity (1 paper, 2020). Accumulation of substantial excess body fat. "From the GWAS, the significant markers associated with obesity-related traits including body weight (CACNA1B, C22orf39, U6, MYH14, PTPN2, SEH1L) and blood sugar (PRSS55, GRIK2), were identified." (PMID 33182249, 2020). "We have identified several significant candidate genes associated with obesity-related traits; in particular, CACNA1B gene harboring SNP BICF2P116826 could be a possible candidate gene for canine obesity." (PMID 33182249, 2020).
osteoporosis (1 paper, 2023). A condition of reduced bone mass, with decreased cortical thickness and a decrease in the number and size of the trabeculae of cancellous bone (but normal chemical composition), resulting in increased fracture incidence. "While this pathway has also appeared in analyses of differentially expressed genes in post-menopausal osteoporosis, roles of specific differential genes, such as Cplx2, Cacna1b, and Dnm1, have not been investigated." (PMID 36788807, 2023).
prostate carcinoma (1 paper, 2017). A carcinoma that arises from epithelial cells of the prostate gland. "CACNA1B (Cav2.2) is the only member in N-type VGCC family, and CACNA1B (Cav2.2) overexpression has been detected in breast and prostate cancer, and it represents a novel therapeutic target for the treatment of breast and prostate cancer." (PMID 28127114, 2017).
rectal cancer (1 paper, 2023). A primary or metastatic malignant neoplasm that affects the rectum. "Interestingly, this miRNA regulates unique genes from all three anatomical locations, including CHGB in the right colon, CACNA1B and GLRA3 in the left colon, and TFAP2B in rectal cancer." (PMID 37987361, 2023).
West syndrome (1 paper, 2025). "It should be emphasized that in the patient with West syndrome, a heterozygous CACNA1B variant was found and considered a cause of West syndrome, though this genotype is not a classical cause for West syndrome." (PMID 40678184, 2025).